RNU6-1047P (RNA, U6 small nuclear 1047, pseudogene)
Gene: Small nuclear RNA gene on chromosome 3 (127,240,968 to 127,241,074, reverse strand). Ensembl gene ENSG00000201288.
Homologues: Orthologues: chimpanzee U6 (98% identical), macaque U6 (88% identical), guinea pig U6 (79% identical), pig U6 (77% identical). Paralogues in human: RNU6-797P (90% identical), RNU6-1287P (88% identical), RNU6-1123P (87% identical), RNU6-175P (87% identical), RNU6-1091P (86% identical), RNU6-1094P (86% identical), RNU6-1152P (86% identical), RNU6-115P (86% identical), RNU6-1209P (86% identical), RNU6-393P (86% identical), RNU6-41P (86% identical), RNU6-643P (86% identical), and 1286 more.